CD4 (CD4 molecule)
Diseases named in the same sentence as CD4 in open-access papers (continued):
Sharing a sentence is not in itself a finding about the gene and the disease.
tumor (continued). "CBD enhanced infiltration of CD4+T and CD8+T cells, CD19+B cells, NK cells, and M1-like macrophages into the primary tumors of immunocompetent syngeneic mice models, implicating an enhanced anti-tumor immune response." (PMID 40475776, 2025). "Guo and colleagues conducted the first study to combine antiOX40 with antiPD-1 in an ovarian cancer model; the regimen expanded CD4+ and CD8+ T cells, reduced Treg and MDSC numbers, induced a local immunostimulatory milieu, and markedly inhibited tumor development." (PMID 41561762, 2025). "Detailed statistical analyses of the CD4 + and CD8 + positive rates demonstrated that the HER2-CXCR5-CCR6-CAR T group had infiltration rates of 5.4% for CD4 + CAR T and 8.8% for CD8 + CAR T cells in the tumor tissue." (PMID 40764989, 2025). "Preclinical studies have shown that treatment with dendritic cells (DCs) engineered to express the chemokine CCL21 can enhance the infiltration of DCs, CD4+, and CD8+ T cells into the lung tumor microenvironment (TME), thereby effectively reducing tumor burden." (PMID 40428349, 2025). "In this study, we sought to determine whether CD4+ and CD8+ T cell responses elicited by subunit vaccines could be harnessed in the immune-suppressed TME for anti-tumor therapy." (PMID 40280970, 2025). "Tregs tend to express a distinct TCR repertoire to conventional CD4+ T cells for the top expanded clones, suggesting that dominant Treg clones in tumours do not arise from peripheral conversion of highly expanded conventional T cell (Tconv) clones." (PMID 40801654, 2025). "Next, CD3+CD8+ T cell, CD4+FOXP3+ TReg, PDL1Tumor, NOS2Tumor, COX2Tumor, IDO1, and B7H4 density heatmaps were spatially examined relative to stroma as well as viable and necrotic annotated tumor regions." (PMID 40663402, 2025). "Therefore, we simultaneously used flow cytometry to analyze CD4+ T cells and CD8+ T cells in the tumor site to understand the antitumor activity of T lymphocytes after NOSH@PEG-HCuSNPs combined treatment." (PMID 39995577, 2025). "Dendritic cells, CD4+ T cells, and CD8+ T cells play crucial roles in initiating and sustaining anti-tumor immunity, suggesting that NTRK3 may enhance immune surveillance and contribute to a more favorable immune landscape in BC." (PMID 40142285, 2025). "VISTA acts as a ligand on tumor cells and mediates negative immunomodulation by inhibiting CD4+ and CD8+ T‐cell activity and suppressing immune cell activity." (PMID 40452814, 2025). "In addition, autophagy dependent degradation of exogenous and endogenous antigens is required for CD4 + helper and CD8 + cytotoxic T cell stimulation through cross-presentation of antigens, including tumor antigens, on HLA class I." (PMID 39928678, 2025). "Notably, we discovered a striking phenomenon: CD4+ and CD8+ T cells were significantly reduced in tumor tissues, whereas epithelial cells, Tregs, and macrophages exhibited increased abundance." (PMID 40698080, 2025). "This imbalance between CD4+ and CD8+ T cells may accelerate tumor progression and serve as a valuable prognostic indicator." (PMID 40699668, 2025). "Treg cells, derived from naive CD4+ T cells independently by TGF-β,are immunosuppressive cells that regulate immune response intensity, mitigate immune injury, mediate immune evasion through anti-tumor immune suppression, and promote tumor progression." (PMID 40166682, 2025). "Many of these pathways were similarly predicted for CD4+ TEMRA cell communication with spatially-confirmed co-localised cell populations, suggesting that CD4+ TEMRA and CD8+ TEMRA cells may share similar topological interaction profiles within VS tumours." (PMID 40140675, 2025). "We found that the majority (CAR1, CAR2, CAR4, CAR5) but not all of our CAR T candidates had potent anti-tumor activity, and exhibited CD4:CD8 ratios of ~1.5." (PMID 40931013, 2025).
tumor (continued). "Furthermore, we analyzed the infiltration of CD4+ and CD8+ T cells within the tumor microenvironment and found that their levels were consistent with those detected in the spleen." (PMID 40426190, 2025). "Second, unlike checkpoint inhibitors that only stimulate T cell activation, IL-1 ligands can activate NK cells, in addition to CD4+ and CD8+ T cells suggesting a more broad anti-tumor immune cell profile may be stimulated." (PMID 40169985, 2025). "Notably, collagen deposition in the high-SMIM25 group appeared to influence the distribution of immune cells, with significantly higher CD4 and CD8 expression in the stromal region compared to the tumor region (p < 0.05)." (PMID 41020815, 2025). "In addition, A. muciniphila promotes the infiltration of CD4+ CCR9+ CXCR3+ T cells into the tumor site, thereby supporting a strong Th1-skewed immune response—an essential component for effective tumor control." (PMID 41030253, 2025). "Despite immune checkpoint blockade, tumor-specific CD4+ T cells from NR patients therefore failed to maintain their effector functions and acquired an exhausted phenotype." (PMID 39794349, 2025). "Unlike highly functional Trp1 T cells, CD4+ T cells in most other tumor models exhibit hyporesponsiveness, largely due to the immunosuppressive TME." (PMID 40634636, 2025). "Tumour-infiltrating CD4+ T cells, irrespective of FOXP3 expression, exhibited elevated CD25 levels, suggesting an activated state." (PMID 41514641, 2025). "The priming of antigen‐specific CD4+ and CD8+ T‐cell responses results in the expansion of T helper cells and cytotoxic T lymphocytes, respectively, which infiltrate the tumor sites and destroy tumor cells upon antigen recognition." (PMID 40726054, 2025). "Overall, high LHPP expression was significantly associated with altered tumor immune infiltration characteristics, showing a positive correlation with the infiltration abundance of CD3+, CD4+, CD45+ T cells, and CD8+, in both the center of the tumor and the invasive margin." (PMID 40240758, 2025). "This, in turn, could recruit MDSCs and naïve T cells, potentially contributing to the increase in CD4+ T cells and the decrease in CD8+ T cells, which may play a critical role in the development of an immunosuppressive tumor microenvironment." (PMID 39891284, 2025). "Here, we assessed the ability of the IPV pipeline to identify tumor specific immunogenic peptides – regardless of the HLA restriction or CD4/CD8 phenotype – in a practical setting with limited blood volumes from patients." (PMID 40103827, 2025). "Moreover, the infiltration of both human CD4+ and CD8+ T cells in tumor lesions of nEL vaccinated mice were significantly brisker in contrast to those observed in controls." (PMID 40458686, 2025). "The exact mechanism remains debated, but other than peritumoral fibrosis, infiltration of CD4+ and mainly CD8+ was seen in the tumor nests following the biopsy of an MCC case, reinforcing the hypothesis of biopsy-induced T-cell immune stimulation." (PMID 40227764, 2025). "In animal experiments, TSME significantly enhanced the efficacy of αPD-1 monoclonal antibody by remodeling the tumor immune microenvironment (TME): The combination therapy group exhibited increased infiltration of CD8+ and CD4+ T cells and reduced proportions of immunosuppressive Treg cells." (PMID 40621452, 2025). "The absence of C3aR increased tumor-infiltrating neutrophils and CD4+ T lymphocytes, particularly the Th1, Th2, and Th17 subsets, while reducing macrophages." (PMID 41300283, 2025). "However, Tregs have the ability to inhibit CD4+ and CD8+ T cell activity and thus promote tumor growth." (PMID 40191727, 2025). "Finally, we investigated the activation pattern of endogenous CD4+ and CD8+ T cells in the tumor-draining lymph nodes at week 4 (experimental design)." (PMID 40333215, 2025).
tumor (continued). "PMN-MDSC, M-MDSC, NK-cell, CD4+ T-cell, Treg, and macrophage (total, M1-like, or M2-like) levels in the tumor did not significantly change with IL-12 and/or trabectedin treatment, which is in contrast to the splenic results." (PMID 39777457, 2025). "Simultaneous depletion of CD4+ and CD8+ T cells completely abrogated the therapeutic effect of ICIs plus Y33 IC, thus demonstrating that T cells are the predominant immune cells responsible for tumor rejection." (PMID 40789741, 2025). "Furthermore, vaccine-induced activation of CD4+ and CD8+ cells augments tumor-specific immunity while reducing regulatory T cell-mediated suppression." (PMID 41614820, 2025). "Potential immune mechanisms may include CD4+ T cells activating NK cells by secreting IFN-γ, and NK cells releasing antigens to enhance CD4+ T cells by killing tumor cells." (PMID 41394802, 2025). "However, Rfwd3‐triggered decrease in CD4+ T cells, CD8+ T cells, NK cells, and DCs, and increase in MDSCs were suppressed by Trex1 knockdown, suggesting that RFWD3‐induced pro‐tumor immune suppression depends on TREX1." (PMID 41117130, 2025). "Interestingly, we observed CD4+, CD8+ T cells and S100A8/9+ neutrophils within the tumor following combination treatments." (PMID 40568104, 2025). "One possibility is that nontraditional innate cues emanating from tumor cells activate DCs to induce the initial CD4+ priming, although this possibility remains an area of active investigation." (PMID 40279312, 2025). "Subpopulations of adaptive immune lymphocytes involved in recognizing and killing tumor cells including activated CD8 T cell, central memory CD4 T cell, T follicular helper, Activated B cell and immature B cell were less infiltrated in the Cholescore_high patients." (PMID 41174058, 2025). "CD4+ cells, for instance, enhance this response by promoting the production of antibodies from B lymphocytes and facilitating the differentiation of CD8+ cells, which are responsible for recognizing tumor antigens and directly eliminating cancer cells." (PMID 40969267, 2025). "The interaction between CD4+ and CD8+ is important for inducing tumor cell apoptosis." (PMID 40446849, 2025). "This vaccine format not only induced robust dendritic cell maturation but also significantly increased pro-inflammatory cytokines like TNF-alpha, IFN-gamma, and IL-12 in plasma and tumor tissues, leading to enhanced infiltration of CD4+ and CD8+ T cells into the tumor microenvironment." (PMID 40160263, 2025). "Further studies revealed that IFNγ release, rather than perforin, is the primary mechanism of tumor killing by anti-CD19 CD4+ CAR T cells." (PMID 40995371, 2025). "Consistent with this, we observed that naïve CD4+ T cells were abundant in tumor‐draining lymph nodes but largely absent from tumors." (PMID 40847888, 2025). "No significant statistical differences were observed in CD4+ T and NK cell populations across the tumor, spleen, and peripheral blood among the four groups." (PMID 41350707, 2025). "Moreover, we observed an inverse relationship between the degree of tumor differentiation and the expression levels of PD-1, PD-L1, FOXP3, and CD25 (P < 0.05), while a direct relationship was noted for CD4 and CD8 expression levels (P < 0.05)." (PMID 40587482, 2025). "Furthermore, KLRG1 is expressed on at least 80% of these tumor-shared CD4+ T cell clones in the periphery, and KLRG1+ blood populations are highly enriched for tumor-matching clones in ex vivo–expanded CD4+ T cells from paired patient blood and tumors." (PMID 40299576, 2025). "In addition, we measured the distances between CK+ tumor cells and various clusters of CD8+ T cells, CD4+ T cells, or CD68+ TAMs." (PMID 40459946, 2025). "Unlike melanoma, where tumor and immune compartments are distinct, the malignant cells in MF are themselves immune cells—primarily CD4+ memory T-cells—blurring the line between immune activation and tumor persistence." (PMID 40843796, 2025).
tumor (continued). "By integrating the results from these four algorithms, we discovered that BCL10 expression was negatively correlated with tumor-suppressing immune cells, including CD8+ T, CD4+ Th1, and NKT cells, and positively correlated with tumor-promoting immune cells, such as CD4+ Th2 and Treg cells." (PMID 40539049, 2025). "Immunohistochemical staining confirmed increased infiltration of CD4 + T cells, CD8 + T cells, monocyte chemoattractant protein-1, CD80-, and iNOS- positive macrophages into the tumor microenvironment of this group, with a marked reduction in CD206-positive macrophages." (PMID 40836337, 2025). "InForm software was used to perform tissue segmentation (epithelial and stromal regions) and quantify the density and spatial proximity of tumor cells, CD8+ T cells and their subsets (cytotoxic, pre-exhausted and exhausted), as well as CD4+ T cells and their subsets (conventional and regulatory)." (PMID 41622928, 2025). "Thus, tumor samples with these aberrations had higher infiltration levels, especially CD8+ and CD4+ T cells." (PMID 40693457, 2025). "Similarly, ectopic MHC‐II expression in PDAC facilitates antitumour immunity by promoting cytotoxic responses from CD4+ and CD8+ T cells against MHC‐II‐positive tumour cells." (PMID 40673641, 2025). "Similarly, studies on immune cell infiltration have indicated that CD4+ and CD8+ T cells are key players in the modulation of tumour responses to radiation." (PMID 39748197, 2025). "Looking at the differentiation status of CD4+ and CD8+ T cell populations, high frequencies of TTM and TEM subpopulations, representing T cells with increased effector function and cytotoxicity, were particularly noticeable in ascites and tumor samples." (PMID 41221283, 2025). "PB@MC treatment significantly ameliorated CD4+ and CD8+ production, enhanced CD3 expression, and reduced CD206 expression in tumour sections, indicating the activation of T cells and reduced M2-like macrophage infiltration within the tumour microenvironment." (PMID 41044178, 2025). "In contrast to CTLs, the tumor‐infiltrating CD4 T cells from the three mouse groups did not have differences in the cytokine expression profile (not shown)." (PMID 40068101, 2025). "PVR/TIGIT, NECTIN2/CD226, and FAM3C/PDCD1 were relatively more strongly expressed in Plac1+ epi‐CD4+ T cells than Plac1− epi‐CD4+ T cells and PVR was specific for Plac1+ tumor cells, which was subsequently validated in HNSCC cells in vitro and in the TMA cohort by mIF." (PMID 40056047, 2025). "The role of CD4 CTLs in anti-tumor immunity has been underestimated due to the lack of MHC class II expression in most cell types." (PMID 40070836, 2025). "Moreover, studies on CD300a/c expression in human CD4+ memory T cell subsets have demonstrated that CD300a/c+ CD4+ T cells are largely TH1 and produce IFN-γ which is essential for anti-tumor immunity." (PMID 40507267, 2025). "Thus, comprehensive analysis of adaptive immune cells in multiple compartments of high-grade serous OC patients showed that the proportions of tumor-infiltrated CD3+ T cells, especially CD4+ T cell subsets, were diminished compared to both liquid samples." (PMID 41221283, 2025). "The presence of CD4+ Th1 T cells and their secretion of IFN-gamma are critical for the activation and proliferation of CD8+ T cells, promoting a Type I immune environment that facilitates direct tumor cell lysis." (PMID 40006664, 2025). "We first evaluated the frequencies of CD4+ and CD8+ T cells using flow cytometry, calculated as percentage of CD3+ T cells among TILs from tumor samples resected in white light (W‐L GBM) or from tumor samples resected with 5‐ALA‐assisted surgery and from PMNC of nine paired patients for each cohort." (PMID 40498413, 2025).
tumor (continued). "Following antigen recognition by professional antigen presenting cells (APCs) or dendritic cells (DCs), major histocompatibility complex (MHC) proteins, both class I and II, present these processed antigens to activate tumor-specific CD8+ and CD4+ T cells, ultimately leading to tumor cell death." (PMID 40227779, 2025). "We found that the spatial distribution of CD8+ T cells (irrespective of Tim3 status) was influenced by the abundance of G9 in tumor cells, while the distribution of CD4+ T cells was not." (PMID 39910335, 2025). "Using a well-matched cohort of NSCLC tumor tissue from PWH and PWOH, and IMC analysis with preserved tissue architecture, we found that PWH harbored a TME that was consistent with highly exhausted, dysfunctional CD4+ and CD8+ T cells." (PMID 40459946, 2025). "Overall, the results presented in this study shows that endosomal TLR agonists delivered through Qβ VLPs are an effective immunotherapeutic strategy for the activation of APCs (monocyte, pDC, mDC) leading to CD4 + and CD8 + T cell activation and potential anti-tumor immune responses." (PMID 41249948, 2025). "Studies indicate that Moringa oleifera can modulate the tumor microenvironment (TME) by reducing Treg polarization, enhancing NK cell cytotoxicity, and prompting the proliferation and clonal expansion of CD8+ and CD4+ T lymphocytes." (PMID 41516140, 2025). "This provides an unprecedented insight into the ontogeny of the natural spontaneous NeoAg-specific CD4+ T cells responding to progressive tumor growth in the absence of other manipulation and how therapeutic NeoAg vaccination influences this development." (PMID 40196575, 2025). "In addition, neoantigens can activate CD4+ and CD8+ T cells to generate an immune response and have the potential to become new targets of tumor immunotherapy." (PMID 40061134, 2025). "The distinct clustering patterns of immune markers, such as the correlation of CD4 and CD8 cells with inflammatory responses in the tumor interface, have also been reported in the literature, emphasizing the dynamic and heterogeneous nature of the immune microenvironment in MTC." (PMID 40469283, 2025). "CD68 expression has significant negative relation with tumor purity and significant positive correlation with tumor-infiltrating levels of B cell, CD4+ T cell, CD8+ T cell, macrophage, myeloid dendritic cell and cancer associated fibroblast in LIHC." (PMID 40918116, 2025). "In HPV-positive tumor cells, induction of CXCL13 in CD4+ T cells lead to increased secretion of IFN-γ, which contributes to elevated tumor-infiltrating lymphocyte (TIL) counts and improved immune cell infiltration, thereby enhancing the prognosis of HNSCC patients." (PMID 40486875, 2025). "TSLP-mediated tumor protection was mediated by CD8+ and CD4+ T cells." (PMID 40873585, 2025). "NK function in anti‐tumor immunity by recognizing and killing tumor cells without prior sensitization or activation, while CD4+ T cells and CD8+ T cells mediate adaptive immune responses." (PMID 40619603, 2025). "In a prospective study of HR+/HER2− metastatic breast cancer treated with a CDK4/6is plus endocrine therapy, circulating Treg cells and myeloid-derived suppressor cells decreased significantly, while CD4+T cells and cytotoxic CD8+T cells with anti-tumor phenotype increased." (PMID 41463246, 2025). "Considering the finding that tumor cell–derived factors suppressed caspase-8 and GSDMD activation in CD4+ T cells, it will be intriguing to identify and characterize these factors in the TME, which could be potential new targets for cancer immunotherapy." (PMID 40759573, 2025). "Additionally, the density of TIM-1+CD4+ T cells, TIM-1+CD8+ T cells, and TIM-1+B cells in both the tumor primary lesion and TDLNs was observed." (PMID 40519901, 2025). "However, MATEs significantly improved both the individual CD8/CD4 ratio and the intratumoral frequency of tumor-antigen-specific CD8+ T cells indicating an augmented tumor-directed immune response." (PMID 39789356, 2025).